ERFE (erythroferrone)
Diseases named in the same sentence as ERFE in open-access papers (continued):
Sharing a sentence is not in itself a finding about the gene and the disease.
infection (3 papers, 2022 to 2024). The state of being infected such as from the introduction of a foreign agent such as serum, vaccine, antigenic substance or organism. "Nevertheless, the improved erythropoietic performance of Rag2−/− mice was further supported by the expression of erythroferrone (ERFE), which was higher in wild-type mice during infection." (PMID 38892340, 2024). "The significance of these findings will need to be dressed in further studies, but there is no question for a role of erythroferrone during infection in fish." (PMID 35464433, 2022). "Hepcidin, a negative regulator of iron export by suppressing ferroportin, and erythroferrone, a positive regulator of iron export by inhibiting hepcidin synthesis, are involved in the iron metabolism but serum erythroferrone and hepcidin were not altered after the infection." (PMID 37180169, 2023).
tumor (3 papers, 2021 to 2025). "We further validated the associations of ERFE expression with survival in n = 11 tumor types using Cox regression models that adjusted survival data for clinical tumor (TNM) stages and treatments." (PMID 36675239, 2023). "The multivariable analysis confirmed that the high ERFE expression was independently associated with inferior OS in n = 10 tumor types, inferior DSS in n = 8 tumor types, and inferior PFI in n = 7 tumor types." (PMID 36675239, 2023). "Therefore, we further comprehensively assessed the association of multiple immune cell infiltration with ERFE expression in tumor cells." (PMID 36675239, 2023). "In a univariable analysis, ERFE expression was significantly associated with inferior overall survival (OS) and disease-specific survival (DSS) in n = 10 tumor types as well as inferior progression-free interval (PFI) in n = 11 tumor types." (PMID 36675239, 2023). "This suggested a potential role of ERFE overexpression in tumor progression, which was supported by the presence of activated pathways involved in cell cycle progression and DNA replication in our study." (PMID 36675239, 2023). "ERFE was consistently overexpressed in tumor tissue in comparison to the normal tissue controls in 22 out of 33 tumor types." (PMID 36675239, 2023). "In summary, we found that the ERFE gene is widely deregulated in tumor tissues as compared to normal controls." (PMID 36675239, 2023). "We first identified genes that were strongly and positively co-regulated with ERFE at the mRNA expression level (Spearman r > 0.5, p < 0.0001) in at least six tumor types." (PMID 36675239, 2023). "For Cycle Flux Intensity, EPHB4 and ERFE emerge as shared predictors across models; EPHB4 (EPH receptor B4) orchestrates vascular development and tissue remodelling; in oncologic contexts, it frequently connects to angiogenesis and microenvironment-driven tumor progression." (PMID 41411367, 2025).
hematologic diseases (1 paper, 2021). "As a consequence, our findings identify ERFE as a promising new therapeutic target for hematologic diseases associated with bone loss, such as β-thalassemia." (PMID 34002695, 2021).
ERFE also shares sentences with these, for which no sentence is quoted: coronary artery disease (3 papers); metabolic disorders (3); metabolic syndrome (3); type 2 diabetes mellitus (2); atherosclerosis (1); beta thalassemia (1); cardiovascular disease (1); chronic heart failure (1); chronic kidney disease (1); coronary artery stenosis (1); diabetes (1); diabetic nephropathy (1); gestational diabetes mellitus (1); hemochromatosis (1); Hyperglycemia (1); Hyperinsulinemia (1); Impaired glucose tolerance (1); infertile (1); liver cancer (1); malaria (1); mesothelioma (1); Obesity (1); obstructive sleep apnea syndrome (1); pancreatic cancer (1); polycystic ovary syndrome (1); proliferative diabetic retinopathy (1); prostate carcinoma (1); Splenomegaly (1); testicular cancer (1); thymoma (1).